FOSL1 (FOS like 1, AP-1 transcription factor subunit)
Diseases named in the same sentence as FOSL1 in open-access papers (continued):
Sharing a sentence is not in itself a finding about the gene and the disease.
glioblastoma (25 papers, 2010 to 2026). The most malignant astrocytic tumor (WHO grade IV). "Actually, single‐cell and proteomic analyses have indicated that FOSL1 is associated with stemness through the IL‐6 pathway in glioblastoma." (PMID 41556041, 2026). "Consistent with our findings, the expression of FOSL1, another AP‐1 comprising protein, has been found to be associated with mesenchymal features and promote aggressiveness in glioblastoma." (PMID 35851726, 2022). "In addition, miR-4516 was identified as a novel oncogene by targeting PTPN14 in glioblastoma, and stromal loss of miR-4516 could promote FOSL1-dependent proliferation and malignancy of triple-negative breast cancer." (PMID 39737397, 2024). "Fosl1 plays a critical role in regulating glioblastoma cell proliferation, epithelial-mesenchymal transition (EMT), and invasion through the AP-1 signaling pathway." (PMID 41282050, 2025). "Fos-like antigen 1 (FOSL1) promotes proneural to mesenchymal transition (PMT) in glioblastoma stem cells (GSCs) through NF-κB signaling pathway." (PMID 39353894, 2024). "We had previously reported that TRPM7 promotes glioblastoma proliferation and invasion through the upregulation of FOSL1." (PMID 37642779, 2023). "FOSL1 has been identified as an inducing factor for the reprogramming of many different cell types, including melanocytes, glioblastoma cells, and Th17 cells." (PMID 37949219, 2023). "FOSL1 is a key factor in regulating mesenchymal glioblastoma plasticity and contributes to GBM aggressiveness." (PMID 37642779, 2023). "Fos-like antigen 1 (FOSL1) can promote the pre-neural mesenchymal transformation of glioblastoma stem cells through the NF-κB signaling pathway." (PMID 37373484, 2023). "Our study on the role of FOSL1 in stemness was based on data obtained from gene expression analysis in glioblastoma." (PMID 34282187, 2021). "Moreover, we discuss the critical implications of FOSL1 in the diagnosis and treatment of tumors with a special emphasis on glioblastoma, emphasizing its relevance in targeted therapy approaches." (PMID 38791400, 2024). "This may suggest that novel therapeutic strategies able to restore FOSL1 expression may be effective for glioblastoma treatment." (PMID 34282187, 2021). "Here SWIM implicated FOSL1 as a putative master regulator of a core of four master neurodevelopmental transcription factors (i.e., SOX2, SALL2, OLIG2, POU3F2), whose induction was demonstrated to be sufficient to reprogram fully differentiated glioblastoma cells into stem-like cells." (PMID 33785068, 2021). "Supporting evidence from glioblastoma stem cells shows that POSTN enhances self-renewal and malignancy via activation of the αvβ3/PI3K/AKT/β-catenin/FOSL1 pathway, upregulating key stemness markers such as CD133, Nestin, and SOX239." (PMID 40520021, 2025). "In our previous publication, the TCGA database, which contained information on 454 glioblastoma patients, classified as GBM based on the WHO classification, was analyzed for the clinical significance of FOSL1 mRNA expression." (PMID 38791400, 2024). "We found that hsa-mir-33a co-targeting FOSL1 and EN2 has a good predictive value for glioblastoma and skeletal muscle reduction." (PMID 36061185, 2022). "Using SWIM to search for switch genes shared by both analyzed glioblastoma datasets, the authors identified FOS-like transcription factor (FOSL1) as the most promising one." (PMID 34282187, 2021).
prostate carcinoma (23 papers, 2006 to 2025). A carcinoma that arises from epithelial cells of the prostate gland. "In prostate cancer, the expression of miRNA-195-5p decreases abnormally, and its ability to suppress the expression of FOSL1 decreases, which leads to an increase in the content of FOSL1 and promotes invasion and metastasis of the tumor." (PMID 40821785, 2025). "FOSL1 promotes the growth and metastasis of human prostate cancer cells via epithelial mesenchymal transition pathway." (PMID 36741260, 2023). "In addition, it is possible that FOS, which is frequently overexpressed in severe prostate tumor, and FOSL1, which promotes growth and metastasis of prostate cancer cells, are also involved in castration-resistance acquisition." (PMID 37463954, 2023). "In our study, we identified that FOSL1 was a target gene of miR-195-5p and was negatively regulated by miR-195-5p, which was similarly reported by a prior study that concluded that miR-195-5p directly targets FOSL1 to inhibit cell migration and invasion in prostate cancer." (PMID 32199129, 2020). "Moreover, miRNA-130a, acted like a tumor suppressor, has been reported to inhibit the androgen receptor (AR) and mitogen activated protein kinase (MAPK) pathways and target FOS-like antigen 1 (FOSL1) in prostate cancer, and triple-negative breast cancer, respectively." (PMID 31640738, 2019). "In addition, miR-130a acts as a tumor suppressor in prostate cancer and triple-negative breast cancer, inhibiting androgen receptor (AR) and mitogen-activated protein kinase (MAPK) pathways and targeting foS-like antigen 1 (FOSL1)." (PMID 35187064, 2021).
triple-negative breast carcinoma (22 papers, 2014 to 2025). An invasive breast carcinoma which is negative for expression of estrogen receptor (ER), progesterone receptor (PR), and human epidermal growth factor receptor 2 (HER2). "For example, decreased levels of miR-4516 have been linked to enhanced FOSL1-mediated proliferation and aggressiveness in triple-negative breast cancer." (PMID 38930863, 2024). "It has been reported that elevated levels of FOSL1 in triple-negative breast cancer (TNBC) patients are associated with poor survival." (PMID 38791400, 2024). "PKCa and FOSL1 ectopic expression is linked to aggressive triple-negative breast cancers, and reducing FOSL1 levels leads to a mesenchymal–epithelial transition." (PMID 38791400, 2024). "In turn, knocking FOSL1 down by ~75% in the human triple-negative breast cancer cells BT549 results in the upregulation of 263 genes and downregulation of 156 genes." (PMID 35163444, 2022). "Loss of CAF derived EV miR-4516 contributes to the proliferation of triple negative breast cancer cells via repression of FOSL1." (PMID 32957712, 2020). "FOSL1 promotes tumor invasion of triple negative breast cancer and is efficiently inhibited by the multiple kinase inhibitor SKLB646." (PMID 31438567, 2019). "In fact, genome-wide profiling of AP-1–regulated transcription has revealed that c-Jun and FosL1 promote cell invasion through the repression of E-cadherin expression by the transcriptional upregulation of ZEB2 in triple-negative breast cancer cells." (PMID 26754630, 2016). "Additionally, specific upregulation of FOSL1 in triple-negative breast cancer (TNBC) indicated its significant contributions to the progression and metastasis for TNBC." (PMID 32199129, 2020). "FosL1/AP-1 signaling has also been reported to modulate ZEB1/2 and TGF-β expression to induce EMT in triple-negative breast cancer cells." (PMID 26754630, 2016).
breast tumors (21 papers, 2006 to 2024). "TMEM106A, acts as a tumor suppressor and is regulated by promoter hypermethylation in gastric cancer cells, and FOSL1 has been linked to primary breast tumor metastasis." (PMID 32547604, 2020). "Interactions between mouse breast tumor cells and TAMs can change the tumor TME, causing an increase in the expression of FOSL1." (PMID 38791400, 2024). "Similar to the breast tumors, the FOSL1 level positively correlates with tumor grade and suggests poorer survival of the patients with colorectal cancer." (PMID 35163444, 2022). "On the contrary, FOSL1 is detectable only in one-third of the primary low-grade breast tumors." (PMID 35163444, 2022). "FOSL1 is downregulated in breast tumor tissues, in our cohort." (PMID 27857161, 2016). "The reliance on copy number alterations (CNAs) in the FOSL1 gene was noticeably higher in the TNBC subtype compared to luminal tumors, indicating a link with more aggressive phenotypes of breast tumors." (PMID 38791400, 2024). "FOSL1 triggers the activation of the IL-6/JAK/Stat3 signaling pathway, resulting in a malignant switch in breast tumor cells that leads to increased release of pro-angiogenic factors such as MMP-9, VEGF, and TGF-β from the tumor cells." (PMID 38791400, 2024). "We recentlyinvestigated the copy number status of the genes FOSL1,GSTP1 and CCND1 in primary breast tumors withlymph node metastasis (Callegari etal., 2016)." (PMID 30816904, 2019). "CDH1 and ELF3 were expressed at a significantly higher level in cells with an epithelial morphology, whereas FN1, FOSL1, VIM, ZFHX1B, SNAI2, SERPINE1 and TFGB1 showed a higher expression in fibroblastic breast tumour cells." (PMID 16495925, 2006).
head and neck squamous cell carcinoma (18 papers, 2017 to 2025). A squamous cell carcinoma that arises from any of the following anatomic sites: lip and oral cavity, nasal cavity, paranasal sinuses, pharynx, larynx, and salivary glands. "The FOSL1 protein in head and neck squamous cell carcinoma (HNSCC) interacts with specific mediator proteins, resulting in the formation of a functional complex known as a super enhancer." (PMID 39838405, 2025). "FOSL1 (also known as FRA-1) functions downstream of the Wnt signaling pathway and was implicated in promoting metastasis in head and neck squamous cell carcinoma, suggested its role as an oncogene." (PMID 39944827, 2025). "SE-associated gene FOSL1 promotes tumorigenicity and metastasis in head and neck squamous cell carcinoma (HNSCC) by upregulating cancer stemness and pro-metastatic genes, including Snail2 and FOSL1 itself." (PMID 39090713, 2024). "Recent studies have shown that CYTOR interacts with FOSL1 to form phase-separated condensates, which can activate FOSL1-dependent super-enhancers (SEs) to promote tumorigenesis and metastasis in head and neck squamous cell carcinoma (HNSCC)." (PMID 40078192, 2025). "Similarly, in head and neck squamous cell carcinoma, the long noncoding RNA (lncRNA) CYTOR stabilizes FOS Like 1 (FOSL1)-dependent transcriptional condensates at SEs (FOSL1 is an AP-1 TF subunit), promoting SE-driven expression of metastasis-related genes (e.g., MMP9)." (PMID 41323740, 2025). "Another study showed that the expression of the SE-associated oncogene FOSL1 was higher in head and neck squamous cell carcinoma (HNSCC) CSCs than in non-CSCs, which may be related to the preservation of CSC-like characteristics, such as self-renewal, tumorigenesis, and metastasis." (PMID 37501079, 2023).
pancreatic cancer (18 papers, 2007 to 2025). "FOSL1 was recently identified as a novel downstream effector of KRAS and higher FOSL1 expression was associated with poor survival outcome in both lung and pancreatic cancer patients." (PMID 30517129, 2018). "These include the possible repurposing of established FOSL1-targeting agents, such as LY‐1816, which was originally developed for pancreatic cancer, for GBM treatment." (PMID 41423530, 2025). "Mutant KRAS lung and pancreatic cancer patients with high FOSL1 expression had the worst survival outcome." (PMID 34503105, 2021). "A significant upregulation of FOSL1 mRNA in pancreatic cancer tissue compared to normal was observed by meta-analysis." (PMID 28220783, 2017). "In this study, the authors show that lung and pancreatic cancers expressing oncogenic KRAS can be targeted by genetic inhibition of FOSL1, which involves downregulation of genes of the mitotic machinery." (PMID 28220783, 2017). "We investigated the possibility that FRA-1 contributes in vivo to pancreatic cancer progression by evaluating gene expression of FOSL1, which encodes FRA-1, in PDAC samples." (PMID 27220889, 2016). "The inhibition of the downstream transcription factor Fos-like antigen 1 (FOSL1) also seems to be a promising target in KRAS mutant lung and pancreatic cancers." (PMID 35883626, 2022). "Studies have shown that FOSL1 (FRA-1) modulates tumor heterogeneity and EMT plasticity during lung and pancreatic cancer progression." (PMID 34455105, 2021). "High FOSL1 expression identifies mutant KRAS lung and pancreatic cancer patients with the worst survival outcome." (PMID 28220783, 2017). "FOSL1 inhibition is detrimental to both KRAS-driven lung and pancreatic cancer." (PMID 34503105, 2021). "Interestingly, the proposed squamous subtype of pancreatic cancer exhibits high expression of FOSL1, TGFB2, SNAI2, and FN1, which is consistent with the FRA1:EMT phenotype we describe here." (PMID 27220889, 2016).
ovarian carcinoma (16 papers, 2008 to 2025). A malignant neoplasm originating from the surface ovarian epithelium. "Taken together it can be concluded that the FOSL1–miR-134 axis drives a positive feedback loop, promoting ERK/JNK signaling and enhancing chemoresistance in ovarian cancer cells." (PMID 38791400, 2024). "In addition, KLF4 was identified as a putative upstream regulator of drug resistance in ovarian cancer and together with ST3GAL5, SYNE1, CXCL8, HERC5, FOSL1, ARRDC4 merits further studies." (PMID 28473707, 2017). "Whereas, our findings confirm a significant association in Lebanese BC patients between the expression levels of FOSL1, Acyl-CoA synthetase bubblegum family member 1 (ACSBG1), and Chromosome 21 open reading frame 37 (C21orf37) genes with ER/PR expression and family history of ovarian cancer." (PMID 27857161, 2016).
gastric cancer (14 papers, 2017 to 2025). A primary or metastatic malignant neoplasm involving the stomach. "In the present study, we systematically evaluated the relationships of tagging SNPs in FOSL1 gene with gastric cancer risk in a two-stage case-control study in Chinese (Screening stage and Replication stage)." (PMID 28169308, 2017). "Our study revealed that SNP rs1892901 in FOSL1 was associated with the increased risk of gastric cancer." (PMID 28169308, 2017). "Nevertheless, so far there are limited studies focusing on the relationship of genetic variants in FOSL1 with gastric cancer." (PMID 28169308, 2017). "Thus, we investigated the association of seven SNPs in FOSL1 gene with gastric cancer in a two-stage case-control study in Chinese (Screening stage: 1,140 gastric cancer cases and 1,547 controls; Replication stage: 1,006 cases and 2,273 controls)." (PMID 28169308, 2017). "In summary, our study revealed that functional SNP rs1892901 in FOSL1 might affect the expression of FOSL1 and other gastric cancer-related genes, and ultimately modify the gastric cancer risk in Chinese." (PMID 28169308, 2017). "Thus, we investigated the association of seven SNPs in FOSL1 with gastric cancer using case-control design in a two-stage strategy (Screening stage: 1,140 gastric cancer cases and 1,547 controls; Replication stage: 1,006 cases and 2,273 controls)." (PMID 28169308, 2017). "In different tumors, the target of FOSL1 is specific; for example, in gastric cancer, FOSL1 can promote the proliferation of tumor cells through the RAS-ERK (extracellular signal-regulated kinase) and PI3K (phosphatidylinositol 3-kinase)-AKT pathways." (PMID 40821785, 2025). "Of note, pancancer analysis of anatomically distinct solid tumors suggested that c-JUN/JUNB and FOSL1/2 are bona fide canonical AP-1 TF configurations in mesenchymal states of lung, kidney, and stomach cancers." (PMID 34399888, 2021). "In this study, we hypothesized that the SNPs in FOSL1 gene might play an important role in the carcinogenesis and progression of gastric cancer." (PMID 28169308, 2017). "Thus, FOSL1 was up-regulated in gastric cancer and might affect the expression of certain important gastric cancer-related genes, and further affect the development of gastric cancer." (PMID 28169308, 2017). "Thus, FOSL1 may influence the occurrence and development of multiple types of cancers including gastric cancer." (PMID 28169308, 2017). "Totally, SNP rs1892901 may influence the expression of FOSL1 and other gastric cancer-related genes on the basis of some potential mechanisms (including modifying DNA methylation and transcription factor response elements), and ultimately affect the occurrence of gastric cancer." (PMID 28169308, 2017). "However, studies about the relationship between SNPs in FOSL1 and gastric cancer are still lacking." (PMID 28169308, 2017).
lung adenocarcinoma (12 papers, 2015 to 2025). A carcinoma that arises from the lung and is characterized by the presence of malignant glandular epithelial cells. "Recent studies have shown that the FOSL1 may be a potential prognostic marker and target for human lung adenocarcinoma with KRAS mutations." (PMID 40761262, 2025). "In line with our findings, FOSL1 activation has been identified as a prognostic marker in lung adenocarcinomas, and biomedical knowledge-based recommendations predict FOSL1 as a potential marker of osimertinib resistance." (PMID 40414926, 2025). "In contrast to lung adenocarcinoma, survival analysis of the TCGA lung squamous cell carcinoma (LUSC) dataset revealed that the expression levels of BIRC3, CXCL5, DKK1, FOSL1, and MYC exhibited limited association with patient survival." (PMID 39858622, 2025). "While MYC is the key target of JQ1 in hematopoietic cancers, FOSL1 is a major JQ1 target in lung adenocarcinoma and other solid tumors, such as osteosarcoma and childhood sarcoma, in which Fra-1 downregulation phenocopies the effect of the BRD4 inhibitor." (PMID 35326630, 2022). "We have previously shown that lung adenocarcinoma (LAC) is inhibited by JQ1 through suppression of FOSL1, suggesting that the epigenetic landscape of tumor cells from different origins and differentiation states influences BETi response." (PMID 33712563, 2021). "Reduction in FOSL1 expression may be more likely facilitating the effects of bromodomain inhibition in these lung adenocarcinoma cells." (PMID 26485762, 2015). "Specifically, FOSL1, also known as aka FRA-1, a member of Fos family, is required for Kras-induced lung tumorigenesis in vivo, and promotes human lung adenocarcinoma proliferation and survival." (PMID 36046435, 2021). "The expression levels of AREG, BIRC3, DKK1, EREG, FOSL1, MYC, and PLAU are negatively correlated with the survival ratio, and are significantly higher in the TSPX-low lung adenocarcinoma samples, compared to TSPX-high lung adenocarcinoma samples." (PMID 39858622, 2025). "Collectively, our findings suggest that pathologic downregulation of TSPX in NSCLC, especially in lung adenocarcinoma, results in upregulation of AREG, EREG, FOSL1, MYC, and PLAU, thereby potentiating the EGFR signaling pathway and leading to the initiation and/or exacerbation of cancer development." (PMID 39858622, 2025). "Taken together, our results suggest that TSPX may suppress the development and/or progression of lung adenocarcinoma by downregulating AREG, BIRC3, DKK1, EREG, FOSL1, MYC, and PLAU, which could exacerbate lung adenocarcinoma, and upregulating the tumor suppressor CACNA2D2." (PMID 39858622, 2025).